INS (insulin)
Diseases named in the same sentence as INS in open-access papers (continued):
Sharing a sentence is not in itself a finding about the gene and the disease.
Insulin resistance (continued). "Insulin resistance therefore refers to a pathophysiological condition when tissues fail to respond to normal insulin levels, thereby triggering an adaptive compensatory response from the beta cells to release more insulin." (PMID 25071836, 2014). "Type 2 diabetes (T2D) is a metabolic disorder characterized by high blood sugar level in the context of insulin resistance, in which body cells have lost the ability to respond adequately to relatively normal levels of insulin." (PMID 25365428, 2014). "Clinically, the term insulin resistance is utilized to indicate that higher-than-normal circulating levels of insulin are required to maintain normoglycemia." (PMID 25232350, 2014). "To date, differences in the relation of FPG and HbA1c to insulin resistance and insulin secretion have been little described in Chinese population." (PMID 24188743, 2013). "While DAG, ceramide and high saturated fat diet are involved in hepatic insulin resistance, other lipid species variously affect hepatic insulin resistance." (PMID 24264040, 2013). "Both in vivo and in vitro studies have indicated that it was probably the ucOC ingredient that played the leading role in lowering blood sugar, promoting insulin synthesis, and improving insulin resistance." (PMID 23533407, 2013). "Insulin resistance due to type B syndrome and insulin antibodies is reported to respond to immunosuppressants and steroids in case series studies." (PMID 23424687, 2013). "CES1 mRNA expression level in adipose tissue was positively associated with body-mass index (P<0.001), homeostasis model assessment-insulin resistance (P = 0.003) and level of fasting glucose (P = 0.002), insulin (P = 0.006), and triglycerides (P = 0.003)." (PMID 23468884, 2013). "FFAs also successfully established insulin resistance evidenced by the specific impairment of insulin PI3K signaling." (PMID 23840461, 2013). "Insulin resistance will increase appetite and blunt satiety signals; excess circulating glucose will be converted to fat by insulin." (PMID 24367528, 2013). "Insulin resistance is characterized by a decreased ability of insulin sensitive tissues to respond to insulin action." (PMID 23781256, 2013). "Pretreatment with quercetin and Gelam honey extract improved insulin resistance and insulin content by reducing the expression of MAPK, NF-κB, and IRS-1 serine phosphorylation (ser307) and increasing the expression of Akt significantly." (PMID 24324490, 2013). "A role of insulin resistance in memory impairment is supported by the observation that exogenous insulin enhances memory even in individuals with AD." (PMID 23924506, 2013). "Triglycerides and WHR, combined with fasting insulin levels, provide a better estimate of current insulin resistance state and improved identification of individuals with future risk of CVD, compared to HOMA-IR." (PMID 24098646, 2013). "In an effort to identify novel and safe insulin sensitizers, we employed a phenotypic drug discovery approach that uses fat-cell based screens that partly mirror insulin resistance seen in Type 2 diabetic patients." (PMID 24194903, 2013). "HOMA-IR, a strong indicator of the development of insulin resistance, correlated with body and adipose tissue weight, fasting glucose, insulin, C-peptide, leptin and resistin (P < 0.05)." (PMID 23783067, 2013). "In healthy adolescents, insulin resistance progressively increased with increased body mass index (BMI), but the compensatory increase in early insulin secretion was limited." (PMID 24137224, 2013). "A HOMA-IR >1.29 points to the major role of insulin resistance, indicating the need for a treatment aimed at improving tissue sensitivity to insulin." (PMID 23819910, 2013). "Because of the importance of insulin resistance, it is reasonable to think that insulin will be the true variable of interest." (PMID 23815799, 2013).
Insulin resistance (continued). "Patients with adrenal incidentalomas show insulin resistance, but adequately adapted insulin secretion with higher insulin concentrations during a glucose challenge, due to a decreased hepatic insulin extraction." (PMID 24146977, 2013). "It is widely accepted that lower insulin secretion and deterioration of insulin resistance lead to a vicious cycle of glucose toxicity for type 2 diabetes, which involves oxidative stress." (PMID 23691063, 2013). "This work is exciting, as it not only presents a novel role for MG53, but also suggests that muscle insulin signaling has a systemic influence on insulin resistance and the metabolic syndrome." (PMID 24175977, 2013). "In the obese state, blood glucose levels increase and trigger the pancreas to increase insulin production, resulting in hyperinsulinemia, hyperglycemia, and insulin resistance." (PMID 23819063, 2013). "Insulin resistance increases the FFAs flux from the adipocytes to the liver because of the reduced ability of insulin in inhibiting lipolysis." (PMID 24264040, 2013). "Insulin resistance can lead to insufficient production of insulin by the pancreatic β-cells and to the clinical condition known as T2D." (PMID 24176906, 2013). "Our study showed that in patients with abdominal obesity, the NEAT score was negatively correlated with serum insulin levels, suggesting that NEAT is associated with insulin resistance in type 2 diabetic patients with abdominal obesity." (PMID 23711224, 2013). "The insulin-sensitizing agent metformin (MET) is used as a treatment strategy in NAFLD patients due to the role of insulin resistance in the pathogenesis of NAFLD." (PMID 24307947, 2013). "The increased hepatic insulin resistance decreases the ability of insulin to downregulate PEPCK gene expression as we saw in the MS, n-3 PUFAs deficient rats." (PMID 23614006, 2013). "In the present work, patients with insulin resistance at baseline usually had a smaller absolute surgery-induced decrease in insulin sensitivity; the only exception being those with very many complications." (PMID 24188443, 2013). "During insulin-resistance, hyperinsulinemia develops to conuteract the decreased responsiveness of the body to insulin." (PMID 24267821, 2013). "In our group of children born SGA at term (defined as BW SDS below −2 SDS), we have recently found higher insulin levels compared with the controls when adjusted for BMI, indicating early signs of a peripheral insulin resistance." (PMID 23781317, 2013). "In the context of insulin action, M2 macrophages sustain insulin sensitivity by secreting IL-4 and IL-10, while M1 macrophages induce insulin resistance through the secretion of proinflammatory cytokines, such as TNFα." (PMID 23964268, 2013). "Moreover, it has been proved that in the development of type 2 diabetes, hyperinsulinemia could induce an increasing proinsulin-to-insulin (P/I) ratio, and the increased level of proinsulin might be one of causes that induce insulin resistance in hyperinsulinemia." (PMID 23776696, 2013). "Angiotensin II (Ang II) contributes to the pathogenesis of insulin resistance by inducing inhibition of key signalling elements of insulin AKT pathway." (PMID 24400038, 2013). "Accumulating evidence has shown that in the early stage of T2DM, insulin secretion is increased to compensate for insulin resistance." (PMID 24167617, 2013). "The presence of insulin resistance leads to increased beta cell insulin secretion with compensatory hyperinsulinemia." (PMID 23671868, 2013). "Recent studies suggest that skeletal muscle secreted growth factor myostatin plays an important role in regulating insulin signaling and insulin resistance." (PMID 24454989, 2013). "This is the first report that increased gluconeogenesis and glucose intolerance develop in adult offspring after exposure to ethanol during either of the 3 weeks of rat gestation, despite increased insulin levels indicative of insulin resistance." (PMID 23544086, 2013).
Insulin resistance (continued). "In type 2 diabetes, peripheral insulin resistance and impaired insulin secretion from pancreatic β-cells are two important features." (PMID 23936668, 2013). "Insulin resistance (IR), insulin sensitivity and secretion were based on the Homeostasis Model Assessment (HOMA) model." (PMID 23556000, 2013). "Notwithstanding that insulin is a safe and effective drug for achieving glycaemic control, it is a global phenomenon that most T2DM patients resist starting insulin, predominantly because of psychological reasons (termed ‘psychological insulin resistance’)." (PMID 24236071, 2013). "This suppression blunts PPARγ insulin sensitizing functions and leads to insulin resistance via the up-regulated NF-kB signaling pathway." (PMID 23772224, 2013). "Two groups of monogenic defects have been detected in patients with severe insulin resistance manifested in early life, (a) those that affect insulin signaling and (b) those that affect adipocyte development and/or function." (PMID 23766565, 2013). "Hypersensitivity syndrome refers to the clinical situation where insulin resistance develops from insulin antibodies (IAs)." (PMID 23424687, 2013). "RBP4 inhibits insulin-induced phosphorylation of IRS1 suggesting that adipocyte secreting RBP4 induces insulin resistance." (PMID 23781214, 2013). "Insulin resistance is characterized by impaired sensitivity of body tissues to the action of insulin, leading to high circulating insulin levels." (PMID 23463496, 2013). "Adipose tissue insulin resistance is quantified using the index Adipo-IR (FFA × INS) that reflects the inability of insulin to suppress peripheral lipolysis." (PMID 23666091, 2013). "RhoA and its downstream effector, Rho-kinase (ROCK), are involved in the development of insulin resistance, regulation of insulin action and glucose homeostasis." (PMID 23776620, 2013). "Of the different methods used to evaluate insulin resistance, fasting insulinemia and fasting glucose to insulin ratio (FGI) resulted in the highest percentages of insulin-resistant adolescents." (PMID 23363783, 2013). "In our model there are two major hallmarks of insulin resistance: hepatic inflammatory process and alteration of glucose tolerance related to an impairment of insulin signaling." (PMID 23861927, 2013). "Insulin tolerance tests (ITTs) conducted in fasting weanlings and nursing pups are also indicative of peripheral insulin resistance and an increase in peripheral resistance with time fasting." (PMID 24198811, 2013). "Similar to humans with insulin resistance, managed bottlenose dolphins (Tursiops truncatus) diagnosed with hemochromatosis (iron overload) have higher levels of 2 h post-prandial plasma insulin than healthy controls." (PMID 24065958, 2013). "Yuja also contains carotenoids, which have been proposed to improve insulin resistance by stimulating insulin-signaling pathways." (PMID 23762167, 2013). "Intake of sugary beverages and added sugars was highest in clusters 1 and 3, in which the highest levels of insulin and insulin resistance were observed." (PMID 23843779, 2013). "Excess body weight and adiposity are directly correlated with insulin resistance, compensated for by the stimulation of pancreatic insulin secretion, and this commonly results in hyperinsulinemia." (PMID 24073332, 2013). "Insulin resistance was assessed by measurement of fasting circulating insulin levels before and after an oral glucose tolerance test and by HOMA-IR." (PMID 23463496, 2013). "T2D is a quickly growing global metabolic disease characterized by impaired insulin secretion from pancreatic β cells and insulin resistance in liver, muscle, and adipose tissue." (PMID 23781214, 2013). "Both insulin resistance and impaired insulin secretion are known to play important roles in the development of hyperglycemia in patients with type 2 diabetes." (PMID 24358252, 2013).
Insulin resistance (continued). "Adiponectin functions to counter obesity-related metabolic perturbations, such as insulin resistance and leptin resistance, that impact glucose and fatty acid metabolism, alter insulin responses, and increase production of inflammatory cytokines." (PMID 24280167, 2013). "An underlying feature that is present across these common diseases is insulin resistance, which is defined as a decreased ability of insulin to perform its biological functions." (PMID 24358323, 2013). "Since its first comprehensive recognition in 1988, when Reaven described the relation between insulin resistance, plasma insulin levels, glucose intolerance and hypertension, MetS has been subject to a number of operational definitions." (PMID 24330597, 2013). "Control of trauma-induced insulin resistance can be achieved via intravenous infusions of glucose and insulin, while a more practical prevention is to ingest a carbohydrate drink." (PMID 24188443, 2013). "Results on the p-values of correlation analysis using insulin sensitivity indices as dependent variables and insulin resistance related traits and genotypes as independent variables." (PMID 24348460, 2013). "We noted a strong inverse relationship between birth weight and both HOMA and fasting circulating insulin levels, indicating a relatively greater insulin resistance in obese adolescents who were of smaller birth size." (PMID 24555145, 2013). "Insulin resistance is known to be a critical modulator of the insulin response to a stimulus, with insulin resistance increasing insulin release." (PMID 23991163, 2013). "Recently, the impact of carrageenan on glucose tolerance, insulin resistance, and impaired insulin signaling in a mouse model was reported, consistent with the evidence that TLR4-mediated inflammation is involved in diabetes." (PMID 23766559, 2013). "In general, β cells can increase insulin secretion sufficiently to overcome insulin resistance and maintain euglycaemia." (PMID 23675523, 2013). "Meanwhile, emerging evidence emphasizes the role of insulin secretion and insulin resistance in body weight regulation." (PMID 23705645, 2013). "Defective insulin-stimulated translocation of GLUT4, as well as activity underlies the disease states of insulin-resistance and type 2 diabetes." (PMID 23665900, 2013). "We set out to examine this proposition in primary human adipocytes, which are primary target cells of insulin and where attenuated phosphorylation of Ser307 is critical in the pathogenesis of insulin resistance and type 2 diabetes." (PMID 23565163, 2013). "In summary, results of the studies acknowledge that plant polyphenols favorably affect several aspects of diabetes-induced metabolic disorders and modulate carbohydrate metabolism, glucose homeostasis, insulin secretion and insulin resistance." (PMID 23938049, 2013). "SGE treatment produced a similar effect to RGS on insulin resistance, evidenced by reduction of fasting serum insulin levels and improved HOME-IR." (PMID 23476686, 2013). "Cell signalling is impacted, particularly insulin signalling in local and peripheral tissue (e.g., muscle and liver) leading to systemic insulin resistance and sustained elevated circulating insulin levels." (PMID 23573093, 2013). "At the same time, the need of an increased rate of insulin infusion to maintain euglycemia following the operation suggested the development of insulin resistance." (PMID 23840093, 2013). "The old rats seem to compensate the increased metabolic load and obesity-induced insulin resistance by the increase of insulin secretion from pancreas." (PMID 23442260, 2013). "Insulin resistance is characterized by a decrease in the uptake of glucose, especially by insulin target tissues, including adipose tissue and skeletal muscle." (PMID 23935612, 2013). "The effect of obesity on insulin resistance is marked and it has been estimated that insulin sensitivity and glucose effectiveness declines by 30% for every 1 kg increase in body weight." (PMID 24348462, 2013).
Insulin resistance (continued). "In order to tackle insulin resistance, it is important to understand the major insulin-signalling pathways involved and their impact on the regulation of blood glucose levels." (PMID 24324517, 2013). "Fasting serum samples were taken for determination of thyroid function (TSH, FT4, and FT3), along with alanine aminotransferase (ALT), lipid profile, glucose, insulin, and insulin resistance (IR)." (PMID 23431294, 2013). "Though administration of quercetin did not reduce the developed hyperglycemia in STZ model, it significantly reduced the insulin level and improved the insulin resistance in the fructose model." (PMID 23717483, 2013). "Normal β cells can compensate for insulin resistance by increasing insulin secretion, but insufficient compensation leads to the onset of glucose intolerance." (PMID 24324490, 2013). "These mice exhibited an insulin-resistance phenotype, indicating a role for this methyltransferase in signaling in insulin-sensitive tissues." (PMID 23840384, 2013). "Insulin resistance is also closely related to hyperinsulinemia, though high blood glucose is observed in the former while high insulin is observed in the latter." (PMID 24324517, 2013). "Women with PCOS were found to have significantly higher fasting insulin (FI) levels, as well as Insulin resistance index (HOMA-IR) (P < 0.05)." (PMID 23825680, 2013). "We measured lipid profiles, uric acid, insulin, fasting glucose, homeostasis model assessment-insulin resistance (HOMA-IR), and blood pressure." (PMID 23762051, 2013). "Fasting insulin level, insulin-resistance homeostasis model assessment (HOMAIR) score, and area under curve of insulin concentration (AUCINS) were selected for assessing insulin sensitivity." (PMID 24348460, 2013). "Insulin resistance and insulin-secretion derangement are correlated in a stable manner and both play a pivotal role in the onset of Type 2 Diabetes Mellitus (T2DM)." (PMID 23447747, 2013). "It is found that hyperinsulinemia, proinsulin/insulin ratio and the number of apoptotic β-cells were all reduced, and the insulin resistance was improved following 21-days administration of DC260126 in db/db mice." (PMID 23776696, 2013). "One of the leading risk factors for the development of type 2 diabetes is resistance to insulin-stimulated glucose uptake or ‘insulin resistance’." (PMID 23022959, 2013). "An impaired activation of the insulin-signaling pathway results in a decreased responsiveness of target tissues to normal circulating levels of insulin, a condition known as insulin resistance." (PMID 23762820, 2013). "The second aim of the study was to investigate the possible association of muscle FGF21 mRNA with other measures of adiposity and insulin resistance, including peripheral insulin resistance by using an insulin clamp combined with stable isotopes." (PMID 23533568, 2013). "There was a significant trend towards higher insulin concentrations and insulin resistance in subjects with higher body mass index independent from 25-hydroxyvitamin D levels." (PMID 23606841, 2013). "Insulin resistance often results in increased insulin production in an attempt to compensate for the decreased insulin sensitivity." (PMID 23505504, 2013). "Six weeks HFD led to insulin resistance, with a higher demand for insulin to which beta cells started to adapt." (PMID 23441226, 2013). "Obese adolescents were significantly more likely to have higher fasting insulin levels and greater insulin resistance (HOMA) if they were SGA." (PMID 24555145, 2013). "Although proinsulin levels increase together with insulin concentrations in insulin resistance, a raised ratio of proinsulin to insulin, due to a disproportionate release of proinsulin from β-cell, is considered an early marker of islet dysfunction." (PMID 24868254, 2013). "The proinflammatory cytokine TNF-α plays a pivotal role in the pathogenesis of insulin resistance by the impairment of insulin signal transduction in cells and animals." (PMID 23389304, 2013).